ATF4 (activating transcription factor 4)
Diseases named in the same sentence as ATF4 in open-access papers (continued):
Sharing a sentence is not in itself a finding about the gene and the disease.
amyotrophic lateral sclerosis (3 papers, 2013 to 2021). Amyotrophic lateral sclerosis (ALS) is a neurodegenerative disease characterized by progressive muscular paralysis reflecting degeneration of motor neurons in the primary motor cortex, corticospinal tracts, brainstem and spinal cord. "Amyotrophic lateral sclerosis (ALS) patients show increased PERK, ATF6, and IRE1 signaling, with higher levels of CHOP and BiP in the spinal cord, and increases in downstream elements of the UPR such as ATF4, XBP-1, and GRP58." (PMID 34360909, 2021).
asthma (3 papers, 2024). "Whether obese asthma risk factors or stress signals activate the ISR (e.g., activating transcription factor 4 [ATF4]), and subsequently induce a transcriptional program, leading to mitochondrial dysfunction and metabolic reprogramming, remains to be determined." (PMID 38474191, 2024). "An increase in ER stress markers including ATF4, ATF6, CHOP, GRP78, and XBP1 has been detected in those with ovalbumin-induced asthma." (PMID 39295946, 2024).
astrocytoma (3 papers, 2017 to 2020). "In a previous global transcriptome study, we found that JDP2 is induced by CA, which is a phytochemical that activates both Nrf2 and ATF4 in U373MG human astrocytoma cells." (PMID 33108704, 2020). "ATF4 activation by CA was also observed in other human cancer cell lines, such as HeLa, Caco-2, and HepG2 cells, suggesting that CA induction of ATF4 is not restricted to astrocytoma cells, although they exhibited varying CA dose-dependency." (PMID 30959808, 2019).
atrial fibrillation (3 papers, 2018 to 2026). A disorder characterized by an electrocardiographic finding of a supraventricular arrhythmia characterized by the replacement of consistent P waves by rapid oscillations or fibrillatory waves that vary in size, shape and timing and are accompanied by an irregular ventricular response. "Thus, we hypothesized that ATF4 expression might also be elevated in response to atrial fibrillation, a condition that has been associated both with oxidative stress and ER stress." (PMID 30003094, 2018). "In order to clarify ATF4's role in atrial fibrillation in vivo, the study was complemented with an immunohistological analysis of atrial tissue obtained from patients undergoing cardiac surgery." (PMID 30003094, 2018). "Here, we show that ATF4 expression impairs atrial cardiomyocyte survival in an in vitro model of atrial fibrillation." (PMID 30003094, 2018). "An elevated number of ATF4 positive cardiomyocytes was present in tissue specimen obtained from patients with atrial fibrillation compared to patients in sinus rhythm; however, human ATF4 mRNA levels of tissue specimen detected by real-time PCR did not significantly differ between the groups." (PMID 30003094, 2018). "On the contrary, the expression of ATF4 in human atrial cardiomyocytes suggests that ATF4 could be one of the transcription factors that are important for atrial cardiomyocyte survival and apoptosis in atrial fibrillation." (PMID 30003094, 2018). "Moreover, we demonstrate that ATF4 is expressed at relevant levels in atrial cardiomyocytes in vivo and might play an important role in atrial remodeling in response to atrial fibrillation." (PMID 30003094, 2018). "In consistence with the evidence that oxidative stress and ER stress are important components of the atrial cardiomyocyte remodeling process, we further demonstrate that AF induces ATF4 using a cellular model of atrial fibrillation." (PMID 30003094, 2018). "Despite the inherent limitations of an in vitro model of AF, the results presented in this study therefore support the notion that ATF4 could play an important role in the atrial remodeling in atrial fibrillation." (PMID 30003094, 2018).
breast tumors (3 papers, 2019 to 2023). "We noticed high background levels of eIF2α-P and ATF4 in the breast tumors of wild type NEU mice, which was attributed to the expression of the NEU transgene." (PMID 31086176, 2019). "The in vitro and in vivo experiments on breast tumors indicate that ER stress-activated protein kinase R (PKR)-like endoplasmic reticulum kinase (PERK)- activating transcription factor (ATF4) signal axis plays an important role in the survival of tumors and metastasis." (PMID 33597817, 2021). "Also, ATF4 downregulation was associated with decreased P21CIP1 and increased DUSP1 mRNA expression in the mouse breast tumor cells." (PMID 31086176, 2019). "Breast tumors from NEU PKR−/− or NEU eIF2αS/A mice contained low levels of eIF2α-P and ATF4 compared with NEU tumors from wild type mice as indicated by immunoblotting." (PMID 31086176, 2019). "Phosphorylation of JNK1/2 downstream of ATF4 is mediated by the suppression of DUSP1, which plays an important role in the anti-tumor effects of PKR in mouse NEU breast tumors." (PMID 31086176, 2019). "Collectively, the data showed that ATF4 acts downstream of PKR and eIF2α-P in mouse NEU breast tumor cells to upregulate P21CIP1 and increase JNK1/2 phosphorylation via the downregulation of DUSP1." (PMID 31086176, 2019). "Public microarray datasets analysis showed that ATF4 expression was higher in breast tumors treated with chemotherapy than in those not treated with chemotherapy." (PMID 36739602, 2023). "Moreover, ATF4-deficient cells exhibited increased proliferation rates compared with proficient tumor cells implicating ATF4 in the anti-tumor effects of PKR and eIF2α-P in mouse NEU breast tumors." (PMID 31086176, 2019).
chronic kidney disease (3 papers, 2019 to 2025). Impairment of the renal function secondary to chronic kidney damage persisting for three or more months. "Further, T4O inhibited ER stress-induced vascular calcification in chronic kidney disease mice by stimulating SIRT1-mediated inhibition of the PERK PERK-eIF2α-ATF4 pathway." (PMID 40109860, 2025). "This hypothesis is also supported by the study showing that the PERK-eIF2α-ATF4 pathway induced by ER stress may alleviate chronic renal failure-induced hippocampal neuronal damage." (PMID 35103058, 2022). "To confirm the role of ATF4 in a more clinical setting, we examined the acute effects of intravenous iron administration in patients with stable, non-immune chronic kidney disease (CKD), who were receiving iron therapy as part of their routine clinical care." (PMID 31291584, 2019).
colorectal tumor (3 papers, 2022 to 2023). "In this study, we discovered that oridonin increased the ER stress biomarkers ATF4 and CHOP in colorectal tumor cells, as well as intracellular ROS levels, and Ca2+ concentration, ultimately inducing apoptosis." (PMID 37337284, 2023). "Another study indicated that the ATF4 pathway was activated, and the DDIT4 was upregulated to restrict mTOR and promote autophagy after inhibiting glutamine decomposition in colorectal tumor cells." (PMID 35013120, 2022).
cutaneous leishmaniasis (3 papers, 2017 to 2025). Leishmaniasis affecting the skin. "For instance, RNA samples from skin lesions of L. braziliensis-infected patients with cutaneous leishmaniasis revealed elevated ATF4 expression compared with healthy controls, highlighting the role of the PERK/eIF2α/ATF4 axis in human infection." (PMID 40149586, 2025). "This differs from a previous study on human cutaneous leishmaniasis where both CHOP and ATF4 were found to be upregulated." (PMID 35030165, 2022). "To address the clinical relevance of our in vitro mechanistic data, we assayed expression of ATF4, XBP-1 and HO-1 in clinical samples obtained from patients with cutaneous leishmaniasis." (PMID 29213084, 2017).
diffuse large B-cell lymphoma (3 papers, 2020 to 2024). "Reduced ATF4 translation was previously observed in SIRT3-deficient diffuse large B-cell lymphoma cells." (PMID 38395990, 2024). "In diffuse large b-cell lymphoma (DLBCL), ATF4 knockdown was shown to substantially reduce cell proliferation, and it was postulated that ATF4 may function to ameliorate amino acid depletion in these cells caused by the flow of cytosolic amino acids into the TCA cycle." (PMID 36348393, 2022).
fibrosis (3 papers, 2022 to 2025). the formation of excess fibrous connective tissue in an organ or tissue in a reparative or reactive process. "Here, the potential role of ATF4 in tubulointerstitial fibrosis was explored from a metabolic perspective." (PMID 41479926, 2025). "However, the potential role of ATF4 in tubulointerstitial fibrosis remains poorly understood." (PMID 41479926, 2025).
Glucose intolerance (3 papers, 2021 to 2024). Glucose intolerance (GI) can be defined as dysglycemia that comprises both prediabetes and diabetes. "Finally, we previously found that FURIN deficiency in pancreatic β cells leads to severe glucose intolerance caused by altered lysosomal acidification and aberrant activation of the mTORC1/ATF4 pathway." (PMID 34198511, 2021). "Activated PERK pathway probably increases hepatic IR, as evidenced by that liver‐specific depression of the PERK/eIF2α/ATF4 pathway by GADD34 overexpression or ATF4 depletion could improve IR and glucose intolerance in diet‐induced obese (DIO) mice." (PMID 37303813, 2023).
Huntington disease (3 papers, 2013 to 2024). Huntington disease (HD) is a rare neurodegenerative disorder of the central nervous system characterized by unwanted choreatic movements, behavioral and psychiatric disturbances and dementia. "For example, we recently reported that targeting ATF4 does not have any consequences on mutant huntingtin aggregation in Huntingtońs disease, whereas ATF4 deficiency significantly reduces motor recovery after spinal cord injury." (PMID 23874395, 2013).
hyperlipidemia (3 papers, 2017 to 2023). "ATF4 overexpression induces early onset of hyperlipidemia in zebrafish, while hepatic lipogenesis was diminished in fructose-fed ATF4-deficient mice with impacts on downregulation of PPAR-γ, SREBP-1, ACC and FAS." (PMID 33308192, 2020).
hypothyroidism (3 papers, 2017 to 2022). Abnormally low levels of thyroid hormone. "Further, hypothyroidism augmented the expression of ATF4 and GADD153, which activates gene encoding proteins to increase the synthesis of stressed cells leading to oxidative and nitrergic stresses into the cell, as we observed in previous results." (PMID 34295248, 2021).
Infertility (3 papers, 2019 to 2024). "ATF4 expression was also shown to be substantially elevated during early embryogenesis and testis development, which is consistent with spermatogenesis defects observed in ATF4 null mice and resembling infertility phenotypes observed in ALKBH5-deficient mice." (PMID 39199320, 2024).
intervertebral disc degeneration (3 papers, 2018 to 2025). "Studies have demonstrated that mesenchymal stem cell-derived exosomes suppress ER stress (PERK/eIF2α/ATF4/CHOP pathway), thereby reducing nucleus pulposus (NP) cell death and ameliorating intervertebral disc degeneration (IDD)." (PMID 40436859, 2025). "Together, NCDH can alleviate senescence and apoptosis of NPCs by suppressing ROS-dependent ERS via the ATF4-CHOP signaling axis in the hyper-osmolarity microenvironment, thus highlighting the therapeutic potential of NCDH in combating degenerative disc diseases." (PMID 38169592, 2024).
lung squamous cell carcinoma (3 papers, 2020 to 2022). "However, Chang and colleagues showed that PD-L1 protein level is negatively correlated with IRF7 in lung squamous cell cancer tissues, which may result from the effect of PD-1/PD-L1 reverse signaling on eIF2α/ATF4 activation with subsequent downregulation of IRF7 expression." (PMID 34858816, 2021).
lymph node metastasis (3 papers, 2014 to 2022). "Univariate analyses showed that overall survival correlated with TNM stage, lymph node metastasis, and ATF4 expression." (PMID 25078779, 2014). "Our results demonstrated that patients with positive ATF4 expression/lymph node metastasis (+) had poorer overall survival rates compared with those of the other patients (P<0.001)." (PMID 25078779, 2014). "Furthermore, a multivariate Cox regression analysis indicated that ATF4 expression and lymph node metastasis were independent prognostic factors for overall survival." (PMID 25078779, 2014). "Using a tissue microarray, we found that ATF4 overexpression correlated with the TNM stage and lymph node metastasis." (PMID 25078779, 2014). "BTBD3 and ATF4 were found not to be significantly up-regulated with regard to the development of distant or lymph node metastasis (p 0.079 and p 0.119, respectively)." (PMID 32179834, 2020). "In addition, clinical evidence indicated that ATF4 overexpression correlates with TNM stage and lymph node metastasis." (PMID 25078779, 2014).
medulloblastoma (3 papers, 2016 to 2026). A malignant, invasive embryonal neoplasm arising from the cerebellum. "Western blot analysis showed that GADD34 homozygous mutation did not alter the level of p-eIF2α and moderately elevated the level of ATF4 in medulloblastoma in Ptch1+/− mice." (PMID 27802424, 2016). "Western blot analysis showed that GADD34 heterozygous mutation did not change p-eIF2α level, modestly elevated ATF4 level, and moderately increased CHOP level in medulloblastoma in Ptch1+/− mice." (PMID 27802424, 2016).
memory impairment (3 papers, 2020 to 2022). "Considering that the perturbations of the UPP are linked to memory impairment in neurodegenerative diseases such as Alzheimer’s, ATF4 degradation by the UPP might have implications for understanding abnormalities of synaptic plasticity as well." (PMID 33198401, 2020).
non-alcoholic steatohepatitis (3 papers, 2021 to 2023). "Subsequent studies revealed its role in inhibiting bone formation by regulating ATF4 and promoting hepatic stellate cell activation by suppressing Sufu expression in non-alcoholic steatohepatitis, and so on." (PMID 37626043, 2023).
ocular hypertension (3 papers, 2020 to 2025). Abnormally high intraocular pressure. "Genetic or pharmacological inhibition of ATF4-CHOP pathway rescued ocular hypertension in mice, which is associated with decreased ECM deposition and ER stress in the TM." (PMID 34830390, 2021). "We also examined whether ATF4-induced ocular hypertension is associated with induction of ER stress in vivo as observed in human glaucomatous TM tissues." (PMID 33154371, 2020). "Moreover, dominant negative inhibitor of ATF4 reduced Dex-induced protein synthesis and ocular hypertension." (PMID 33154371, 2020). "In summary, we report that the ATF4-CHOP ER stress pathway is activated in human glaucomatous neurodegeneration and a mouse model of ocular hypertension." (PMID 40076484, 2025). "It is interesting to note that inhibition of ATF4 rescues both Dex and mutant MYOC-induced ocular hypertension." (PMID 33154371, 2020).
retinoblastoma (3 papers, 2024 to 2025). A malignant tumor that originates in the nuclear layer of the retina. "RPL41 inhibits the lysosomal trafficking of the ARL5B/SKIP/Kinesin-1 signaling pathway by promoting the degradation of ATF4, thereby suppressing the growth and metastasis of retinoblastoma." (PMID 41451209, 2025). "ATF4 is over-expressed in many tumors including retinoblastoma, and is regarded as a candidate therapeutic target." (PMID 41451209, 2025). "Initial observations from clinical retinoblastoma pathological sections revealed a consistent expression trend, wherein the levels of ATF4 and ARL5B were both lower in normal para-cancerous retinal tissues compared to RB tumor tissues." (PMID 41451209, 2025). "Additionally, ARL5B has been validated as a downstream target gene regulated by the transcription factor ATF4 in retinoblastoma." (PMID 41451209, 2025). "RPL41 down-regulates the expression of ARL5B by degrading ATF4 and the impaired ARL5B-related lysosomal trafficking is a mechanism to inhibit the metastasis of retinoblastoma." (PMID 41451209, 2025). "The western blot results demonstrated that the expression of the marker proteins IRE1α, BiP, p-eIF2α, ATF4, and CHOP was upregulated in a dose-dependent manner in retinoblastoma cells after xanthatin treatment." (PMID 40309730, 2025). "However, anti-ATF4 strategy in cancer therapy has never been tested in vivo due to the lack of systematically usable anti-ATF4 agents, the role of ATF4 in retinoblastoma progression and metastasis remains poorly understood." (PMID 41451209, 2025).
sarcoma (3 papers, 2015 to 2025). A usually aggressive malignant neoplasm of the soft tissue or bone. "Low ATF4 expression was associated with poor outcomes in patients with sarcoma, suggesting an important role for ATF4 disruption in tumorigenesis." (PMID 31534554, 2019). "Further bioinformatics analysis of public databases confirmed ATF4 downregulation in other clinical sarcoma samples." (PMID 31534554, 2019). "Sarcomas derived from GCN2−/− C57BL6 mice specifically demonstrated high levels of PERK activation, while sarcomas derived from GCN2−/− mixed background mice upregulated ATF4 even though eIF2α phosphorylation was reduced." (PMID 26123823, 2015). "The sarcomas displayed compensatory activation of PERK or phospho-eIF2α independent upregulation of ATF4 in order to maintain ISR signaling, indicating that this pathway is critical for tumorigenesis." (PMID 26123823, 2015). "Reduced expression of ATF4 is correlated with poor survival of patients with sarcoma." (PMID 31534554, 2019). "We next examined the expression of 19 genes in different bone-related sarcomas using The Cancer Genome Atlas (TCGA) database and found relatively high HSPA5 and ATF4 mRNA levels in tumor tissues and significantly low CBLC and RET expression levels." (PMID 31534554, 2019). "A heatmap of all these genes involved in cell fate determination revealed various changes in their mRNA levels when ATF4 was overexpressed, with the most distinct downregulation of BCL2, one prominent gene that is highly expressed in bone-related sarcoma samples." (PMID 31534554, 2019). "We first measured ATF4 copy number in GCN2+/+ and GCN2−/− sarcomas with a TaqMan copy number assay." (PMID 26123823, 2015). "Thus, it appears that GCN2−/− sarcomas do not directly or indirectly upregulate ATF4 transcript levels." (PMID 26123823, 2015). "This analysis reveals that many ATF4 target genes are overexpressed in human patient samples, indicating that ISR activation in sarcomas is a clinically relevant phenomenon and not just restricted to mouse models." (PMID 26123823, 2015). "The lack of substantial differences in ATF4 copy number, transcript levels, and coding sequence between GCN2+/+ and GCN2−/− mixed background sarcomas suggests that another factor is regulating ATF4 protein expression in trans to maintain ATF4 levels in GCN2−/− tumors." (PMID 26123823, 2015).
T-cell acute lymphoblastic leukemia (3 papers, 2015 to 2025). Acute lymphoblastic leukemia of T-cell origin. "To address whether ATF4 regulates ULBP1 in other cell types, we mutated ATF4 in the K-562 chronic myelogenous leukemia cell line and the Jurkat acute T-cell leukemia cell line." (PMID 26565589, 2015).
acute pancreatitis (2 papers, 2021 to 2024). An acute inflammatory process that leads to necrosis of the pancreatic parenchyma. "The ATF4-mediated histone deacetylase HDAC1 promotes the progression of acute pancreatitis." (PMID 38913045, 2024).
aneurysm (2 papers, 2023 to 2024). Bulging or ballooning in an area of an artery secondary to arterial wall weakening. "Four weeks after AngII infusion, the ATF4-knockdown (AngII+sh-ATF4) mice showed significantly smaller aneurysm formation compared with ApoE-/- (AngII) mice, while ATF4-overexpression (AngII+oe-ATF4) mice showed aggravated AAA formation." (PMID 38913045, 2024). "ATF4 knockdown significantly attenuated aneurysm formation in experimental mouse model of AAA, while ATF4 overexpression promoted the development of AAA." (PMID 38913045, 2024).